CUL2 (cullin 2)
Description:
Core component of multiple cullin-RING-based ECS (ElonginB/C-CUL2/5-SOCS-box protein) E3 ubiquitin-protein ligase complexes, which mediate the ubiquitination of target proteins. CUL2 serves as a rigid scaffold in the complex and may contribute to catalysis through positioning of the substrate and the E2 ubiquitin-conjugating enzyme. The E3 ubiquitin-protein ligase activity of the complex is dependent on the neddylation of the cullin subunit and is inhibited by the association of the deneddylated cullin subunit with TIP120A/CAND1. The functional specificity of the ECS complex depends on the substrate recognition component. ECS(VHL) mediates the ubiquitination of hypoxia-inducible factor (HIF). A number of ECS complexes (containing either KLHDC2, KLHDC3, KLHDC10, APPBP2, FEM1A, FEM1B or FEM1C as substrate-recognition component) are part of the DesCEND (destruction via C-end degrons) pathway, which recognizes a C-degron located at the extreme C terminus of target proteins, leading to their ubiquitination and degradation. ECS complexes and ARIH1 collaborate in tandem to mediate ubiquitination of target proteins. ECS(LRR1) ubiquitinates MCM7 and promotes CMG replisome disassembly by VCP and chromatin extraction during S-phase (By similarity).
Tractability: Small molecule: a structure with a bound ligand is known. PROTAC: UniProt records ubiquitination sites on it; ubiquitination databases record sites on it; its protein half-life has been measured.
Gene: Protein-coding gene on chromosome 10 (35,008,504 to 35,127,006, reverse strand). Ensembl gene ENSG00000108094.
Subcellular location: Nucleus
Subcellular location (Human Protein Atlas): Nucleoplasm
Pathways (Reactome):
Metabolism of proteins: Neddylation; Ribosome Quality Control (RQC) complex extracts and degrades nascent peptide
Cellular responses to stimuli: Oxygen-dependent proline hydroxylation of Hypoxia-inducible Factor Alpha
Developmental Biology: Regulation of expression of SLITs and ROBOs
Immune System: Antigen processing: Ubiquitination & Proteasome degradation
Gene Ontology:
Molecular function: protein binding; ubiquitin ligase complex scaffold activity; ubiquitin protein ligase binding; ubiquitin-protein transferase activity
Biological process: ubiquitin-dependent protein catabolic process via the C-end degron rule pathway; G1/S transition of mitotic cell cycle; intrinsic apoptotic signaling pathway; negative regulation of beige fat cell differentiation; negative regulation of DNA-templated DNA replication; negative regulation of transcription by RNA polymerase II; proteasome-mediated ubiquitin-dependent protein catabolic process; protein ubiquitination; rescue of stalled ribosome; ribosome-associated ubiquitin-dependent protein catabolic process; SCF-dependent proteasomal ubiquitin-dependent protein catabolic process; ubiquitin-dependent protein catabolic process
Cellular component: Cul2-RING ubiquitin ligase complex; nucleoplasm; cytoplasm; cytosol; nucleus; SCF ubiquitin ligase complex; cullin-RING ubiquitin ligase complex; nuclear lumen; nucleolus
Genetic constraint (gnomAD): Loss-of-function variants: 7 observed, 43.16 expected, observed/expected ratio (o/e) 0.16, 90% interval 0.091 to 0.31. The upper end of that interval is the gene's LOEUF score, 0.31, which puts it in group 1 of 6, group 1 being the genes least tolerant of losing a copy. Missense variants: 309 observed, 458.91 expected, observed/expected ratio (o/e) 0.67, 90% interval 0.61 to 0.74. Synonymous variants: 128 observed, 153.62 expected, observed/expected ratio (o/e) 0.83, 90% interval 0.72 to 0.96.
Homologues: Orthologues: macaque CUL2 (100% identical), chimpanzee CUL2 (99% identical), pig CUL2 (99% identical), dog CUL2 (99% identical), rabbit CUL2 (99% identical), guinea pig CUL2 (98% identical), rat Cul2 (98% identical), mouse Cul2 (97% identical), tropical clawed frog cul2 (93% identical), zebrafish cul2 (91% identical), Drosophila melanogaster Cul2 (50% identical), Caenorhabditis elegans cul-2 (44% identical). Paralogues in human: CUL1 (38% identical), CUL4B (29% identical), CUL4A (29% identical), CUL5 (28% identical), CUL3 (27% identical), ANAPC2 (14% identical), CACUL1 (7% identical).
Diseases named in the same sentence as CUL2 in open-access papers:
CUL2 is named in the same sentence as 60 diseases in open-access papers, as found by Europe PMC text mining. Sharing a sentence is not in itself a finding about the gene and the disease. The quoted sentences say what the papers report.
hepatocellular carcinoma (9 papers, 2021 to 2025). A malignant tumor that arises from hepatocytes. "Previous studies in mammals have demonstrated that the Cul2 gene can encode the product of Cul2 circRNA to modulate epithelial–mesenchymal transition in hepatocellular carcinoma, gastric cancer malignant transformation, or colorectal cancer development." (PMID 40141268, 2025). "EMT mediated by overexpression of TWIST is associated with hepatocellular carcinoma (HCC) cell invasion and metastasis, possibly through the mediation of Cullin 2 (Cul2) circular RNA to increase the expression of vimentin." (PMID 34298613, 2021). "In this study, a focus was on the downstream candidate miRNA of Circ-CUL2 (miR-888-5p), which has been manifested the elevation in hepatocellular carcinoma and acceleration of cancer cell metastasis." (PMID 35068326, 2022). "Finally, the transcription factor Twist1 was found to bind the Cul2 promoter to selectively promote the expression of Cullin2 (Cul2) circular RNA during the epithelial–mesenchymal transition in hepatocellular carcinoma." (PMID 33397425, 2021). "In hepatoma, Twist1 can promote vimentin expression, and it has been verified that Twist1 is combined with a circular RNA, the promoter region of CUL2 (Cullin-2), and promotes the mRNA of vimentin by adsorbing the microRNA targeting vimentin degradation, resulting in EET." (PMID 33397409, 2021).
colorectal cancer (7 papers, 2020 to 2025). A primary or metastatic malignant neoplasm that affects the colon or rectum. "FEM1C, though still poorly understood in this context, belongs to the highly conserved VHL-box proteins family, involved in cell cycle regulation and cell proliferation via the Cullin 2-RING E3 ubiquitin ligase complex, and its downregulation has been linked to colorectal cancer progression." (PMID 41359656, 2025). "Moreover, both CUL2 and SOX6 are associated with colitis as well, while SERPINB9 and NINJ2 have been associated with colorectal cancer." (PMID 35371111, 2022). "Whether a large number of differentially expressed circRNAs, such as circ-3823, circ-IL4R, and circ-CUL2 in colorectal cancer, could become effective targets for curcumin in the treatment of colorectal cancer remains to be further clarified." (PMID 36291546, 2022).
virus infection (6 papers, 2016 to 2022). "Knockdown of CUL2 and to a lesser extent CUL1 using siRNA stabilized SAMHD1 in normal fibroblasts and inhibited SAMHD1 loss during virus infection." (PMID 32850489, 2020). "Again in the circumstance of virus infection, CUL2 functions mainly as a scaffold protein of E3 ubiquitin ligase." (PMID 27153550, 2016). "As different viral proteins co-opt Cul2 to evade host defense, inhibiting their activities might help us fight various viral infections." (PMID 27222660, 2016).
cervical cancer (5 papers, 2016 to 2024). A primary or metastatic malignant neoplasm involving the cervix. "Here, we showed that CUL2 expression was obviously higher in HPV16 positive cervical cancer cells and tissues that that in other positive high-risk genotypes." (PMID 27153550, 2016). "Dysregulation of microRNAs (miRNAs) is induced during tumorigenesis; however, the association between miRNA networks and CUL2, specific to cervical cancer, remains unknown." (PMID 32742484, 2020). "CUL2 has a significant role in the development and prognosis of cervical cancer and other malignant tumors." (PMID 37397007, 2023). "Meanwhile, overexpression of miR-154-5p restrained the growth and metastasis of cervical cancer by silencing CUL2 in vivo." (PMID 37397007, 2023). "Next, we searched the pan-cancer expression profile of CUL2 using the online database GEPIA and discovered that CUL2 expression was higher in CESC (cervical cancer, including cervical squamous cell carcinoma and adenocarcinoma) than in normal cervical tissue." (PMID 37397007, 2023). "In conclusion, miR-154-5p restrained the growth and metastasis of cervical cancer by directly silencing CUL2." (PMID 37397007, 2023). "In this study, the tumor tissues were dissected, aliquoted in tissue tubes, and stored at −80 °C to detect miR-154-5p and CUL2 expression levels to assess the effects of miR-154-5p on the occurrence and development of cervical cancer in vivo." (PMID 37397007, 2023). "We used bioinformatics analysis to predict and the dual-luciferase reporter assay to confirm that CUL2 is a target of miR-154-5p in cervical cancer." (PMID 32742484, 2020). "Mechanistic analyses revealed that miR-154-5p plays a tumor-suppressive role in cervical cancer through mediating pRb expression by targeting CUL2 3'UTR." (PMID 32742484, 2020). "This suggests that the miRNA-mediated CUL2 regulation is an important target for blocking cervical cancer." (PMID 32742484, 2020). "Here, we demonstrated that CUL2 was specifically overexpressed in HPV16 positive cervical cancer cells and tissues, and CUL2 expression was significantly increased along with the cervical lesion progression and positively correlated with HPV16 E7." (PMID 27153550, 2016). "Similar to the action of CUL2 inhibition, miR-424 overexpression reduced cell growth by blocking cell cycle progression and inducing apoptosis in cervical cancer cells, as we previously reported." (PMID 27153550, 2016). "Thus, in HPV16-induced cervical cancer, CUL2 may play a different role from other high-risk HPVs." (PMID 27153550, 2016). "HPV16 E7-CUL2 interaction recruits CUL2 and the activation of regulatory loop among CUL2, E2F1, and miR-424 produces the persistent CUL2 overexpression, which consequently promotes the growth of cervical cancer cells." (PMID 27153550, 2016). "Considering a stronger carcinogenicity of HPV16 than that of others, it should be valuable to explore the expression, associated regulating mechanism, and carcinogenic potential of CUL2 itself in HPV16-induced cervical cancer." (PMID 27153550, 2016). "Additionally, miR-154-5p reduced CUL2 level, and overexpression of CUL2 influenced the effect of miR-154-5p in cervical cancer." (PMID 37397007, 2023). "It is clear that CUL2 plays a critical role in the process of HPV16-induced cervical carcinoma." (PMID 37397007, 2023). "Therefore, CUL2-mediated regulation of HPV16 E7-induced pRb degradation is a critical step for the progression of HPV16 infection into cervical cancer." (PMID 32742484, 2020). "Recent studies have found that in cervical cancer cells, miR-424 binds to CUL2 mRNA, and that overexpression of miR-424 decreases CUL2 mRNA and protein expression, thereby inhibiting cell proliferation, migration and invasion, promoting cell cycle arrest in the G1/S phase 19." (PMID 32742484, 2020). "However, reports on the correlation between miRNA expression and CUL2 regulation in the context of cervical cancer are rare." (PMID 32742484, 2020).
cervical cancer (continued). "Our findings suggest that CUL2 may play the direct oncogenic role in the development of HPV16-induced cervical cancer." (PMID 27153550, 2016). "Thus, our results suggest that CUL2 overexpression driven by CUL2/E2F1/miR-424 regulatory loop exists specifically in HPV16 infected cervical cancer cells." (PMID 27153550, 2016). "Thus, the tumor suppressor effects of miR-154-5p on cervical cancer might have been altered by the expression of CUL2." (PMID 37397007, 2023). "Therefore, insight into the regulatory networks of miRNA that target CUL2 during CIN progression may help to identify their contribution to the pathogenesis of cervical cancer." (PMID 32742484, 2020). "Thus, we supposed there might be a feedback regulatory loop between miR-424 and CUL2 in HPV16 positive cervical cancer cells." (PMID 27153550, 2016). "The dual luciferase reporter assay confirmed the targeted regulation effect of miR-154-5p and CUL2, and preliminarily discussed the anti-cancer effect role of miR-154-5p mediated CUL2 in HPV16-positive cervical cancer cells using transient transfection method." (PMID 37397007, 2023). "In addition, lncRNA LINC00997 was shown to activate the MAPK pathway-associated protein CUL2 by interacting with miR574-3p, demonstrating that the LINC00997/miR-574-3p/CUL2 axis contributes to proliferation, migration, invasion, and autophagy by activation of MAPK signaling in cervical cancer." (PMID 35406713, 2022). "We further verified that CUL2 bound to E2F1 and promoted E2F1 expression, and E2F1 was required for CUL2 mediated miR-424 inhibition in cervical cancer cells." (PMID 27153550, 2016). "Our results indicate the existence of a regulatory loop among CUL2, E2F1, and miR-424 in HPV16 positive cervical cancer cells." (PMID 27153550, 2016). "Overall, this study comprehensively revealed that miR-154-5p silenced CUL2 expression and inhibited translation, thus weakening the proliferation and migration capabilities of HPV16-positive cervical cancer cells, ultimately inhibiting cervical carcinoma growth and metastasis." (PMID 37397007, 2023). "Contrarily to the pattern of CUL2 and HPV16 E7 expression, miR-424 expression was decreased during the stepwise progression from cervical normal epithelium throughout precancer lesions to cervical cancer with HPV16 infection." (PMID 27153550, 2016). "Therefore, this study chose miR-154-5p as the “main variable molecule,” and conducted both in vivo and in vitro experiments to clarify the effects of miR-154-5p targeting CUL2 on the evolution and metastasis of cervical cancer and identify new molecular targets for HPV16-induced cervical cancer." (PMID 37397007, 2023). "We initially examined CUL2 and HPV16 E7 mRNA expressions using qRT-PCR in a panel of 137 cervical specimens, including 36 HPV negative and 37 HPV16 positive normal cervical tissues, 33 HPV16 positive CIN 2-3, and 31 HPV16 positive invasive cervical cancer tissues." (PMID 27153550, 2016). "Moreover, CUL2 was gradually increased from normal cervix without HPV infection throughout precancer lesions to cervical cancer tissues with HPV16 infection, and positively correlated with HPV16 E7 expression." (PMID 27153550, 2016). "However, in vivo evidence on whether miR-154-5p targets CUL2 to regulate cervical cancer is still lacking in the literature." (PMID 37397007, 2023). "Such morphology indicates that CUL2 overexpression specifically exists in HPV16 positive cervical cancer cells and tissues and implies that CUL2 may play a more crucial role in the development of HPV16-induced cervical cancer other than participating in E7-mediated pRb degradation." (PMID 27153550, 2016). "Recent studies revealed that CUL2 participated in the E7-mediated pRb degradation in HPV16, but not other genotypes, infected cervical cancer cells." (PMID 27153550, 2016).
breast carcinoma (3 papers, 2018 to 2022). "For relapse-free survival, breast cancer patients with higher expression of VEGFA, EZH2, CASP3, WWP1, CUL2, and COL3A1 had poorer prognosis." (PMID 35812757, 2022). "It has been reported that CUL1, CUL2, CUL4A and CUL5 are efficiently deNEDDylated by MLN4924 in MCF breast cancer cells." (PMID 35880551, 2022). "In addition, following 6 h treatment with MLN4924, CUL1, CUL2, CUL4A and CUL5 are efficiently deNEDDylated in MCF breast cancer cells." (PMID 35880551, 2022). "We went on to validate the gene expression of the ECV complex genes RBX1, CUL2, TCEB1, and TCEB2 in MCF7 and MDA-MB-231 breast cancer cell lines ectopically overexpressing ∆Np73, and found their downregulation to be consistent with the breast cancer patient data." (PMID 29628507, 2018).
gastric cancer (3 papers, 2018 to 2025). A primary or metastatic malignant neoplasm involving the stomach. "In contrast, CUL2 has been reported to promote the progression of gastric cancer." (PMID 32742484, 2020). "For example, CUL2 overexpression in gastric cancer tissues may be driven, in part, by aberrant levels of miR-574-3p, suggesting a role for the CUL2/miR-424 pathway in promoting growth in cancer cells." (PMID 29594129, 2018).
Obesity (3 papers, 2022 to 2025). Accumulation of substantial excess body fat. "Together, these results suggest that CUL2–APPBP2 deficiency in adipose tissues protects against diet-induced obesity, glucose intolerance, insulin resistance, hepatic steatosis and dyslipidaemia." (PMID 35978186, 2022). "Integrated protein-metabolite network analysis identified OSBPL10, CUL2, and PRTN3 as potential regulators of lipid metabolism and insulin resistance, offering insights into obesity-associated metabolic dysfunction." (PMID 40822952, 2025). "Adipocyte-specifc deletion of Cul2–Appbp2 counteracts obesity, insulin resistance and dyslipidaemia." (PMID 39351529, 2024). "Adipocyte-specific deletion of Cul2 or Appbp2 counteracted diet-induced obesity, glucose intolerance, and insulin resistance while promoting adipocyte thermogenesis." (PMID 39351529, 2024). "Importantly, extended PRDM16 protein stability by adipocyte-specific deletion of CUL2–APPBP2 counteracted diet-induced obesity, glucose intolerance, insulin resistance and dyslipidaemia in mice." (PMID 35978186, 2022).
renal cell carcinoma (3 papers, 2014 to 2022). "Genes of TCEB2, HIF1A, TCEB1, and CUL2 which participated in renal cell carcinoma pathway might be the potential target genes for RCC treatment." (PMID 25091575, 2014). "Genes such as TCEB2, HIF1A, TCEB1, CUL2, and RBX1 were involved in both of the first and the third routes of the renal cell carcinoma pathway." (PMID 25091575, 2014). "TCEB2, HIF1A, TCEB1, CUL2, and RBX1 were involved in the renal cell carcinoma pathway, while TCEB2, HIF1A, TCEB1, and CUL2 had the highest degree in the PPI network." (PMID 25091575, 2014). "Among the protein–protein interaction network, TCEB2, HIF1A, TCEB1, CUL2, RBX1, and PHF17 were hub genes which might be involved in the development of renal cell carcinoma." (PMID 25091575, 2014).
von Hippel-Lindau disease (3 papers, 2016 to 2024). An autosomal dominant disorder caused by pathogenic variants in the VHL gene, leading to an increased risk of various benign and malignant tumors, including hemangioblastomas, retinal hemangiomas, endolymphatic sac tumors, renal cell carcinoma, and pheochromocytomas. "VHL is often mutated in Von Hippel–Lindau disease, possesses E3 ubiquitin ligase activity, and acts as an adaptor of the Cullin-2 (CUL2) RING ubiquitination complex." (PMID 36678835, 2023). "Of the well-known adaptors of E3 ligase, we selected von Hippel-Lindau syndrome (VHL) and HIV-1 virion infectivity factor (VIF), which are adaptors for the complex including elongin B, elongin C, and cullin-2/5 that possesses E3 ubiquitin ligase activity." (PMID 27322423, 2016).
Hepatic fibrosis (2 papers, 2021 to 2023). The presence of excessive fibrous connective tissue in the liver. "For example, microRNA-322/424 regulates LSEC dedifferentiation by targeting the CUL2/HIF-1α pathway to promote liver fibrosis, and correcting these aberrant microRNAs can alleviate liver fibrosis." (PMID 37999580, 2023). "miRNA-322/424 exacerbates hepatic fibrosis by influencing the CUL2/HIF-1α axis to regulate angiogenesis." (PMID 34867446, 2021).
Insulin resistance (2 papers, 2022 to 2024). Increased resistance towards insulin, that is, diminished effectiveness of insulin in reducing blood glucose levels. "In agreement with emerging evidence regarding the UCP1-independent role of beige fat18,19,36, fat-specific CUL2–APPBP2 blockade not only improved glucose intolerance, insulin resistance and lipid profile, but also suppressed WAT inflammation and fibrosis before changes in body weight." (PMID 35978186, 2022).